MYD88 (MYD88 innate immune signal transduction adaptor)
Diseases named in the same sentence as MYD88 in open-access papers (continued):
Sharing a sentence is not in itself a finding about the gene and the disease.
infection (continued). "The resistance to infection with T. cruzi is known to depend on appropriate MyD88 signaling after stimulation of TLR2 and TLR9, and TLR4." (PMID 22348160, 2012). "The results reported here confirm the importance of MyD88 in the control of infection and extend those findings to include three tissues; spleen, liver and lung." (PMID 22973560, 2012). "We observed infection-induced DEVDase activity and caspase-7 cleavage in myd88−/− and rip2k−/− BMDM at levels comparable to WT BMDM." (PMID 22807671, 2012). "Authors suggest that TLR9 has a primary role in the MyD88-dependent induction of IL12/IFNγ synthesis during infection." (PMID 21869919, 2012). "This suggests that MyD88-dependent mechanisms are responsible for regulating cytokine/chemokine levels during late infection, the identity of which remains to be defined." (PMID 22879997, 2012). "In contrast, recovery of exudate macrophages from the airways of Myd88−/− or Tlr3−/− mice compared to C57BL/6 controls was similar 3 days after infection." (PMID 22496659, 2012). "In contrast, IgG levels in MyD88−/− mice exhibit a significant reduction in titer over the course of infection." (PMID 22973560, 2012). "Bacterial burdens on both infected catheters and surrounding tissues were significantly elevated in MyD88 KO compared to WT animals at days 3 and 7 post-infection and extended out to day 14 in biofilm-infected tissues of the former." (PMID 22879997, 2012). "The expression of several proinflammatory mediators, including IL-6, IFN-γ, and CXCL1 was significantly reduced in MyD88 KO mice, primarily at the later stages of infection." (PMID 22879997, 2012). "The contribution of either elevated IgA or suppressed IgG to the inability of MyD88 knockouts to control infection is under investigation." (PMID 22973560, 2012). "First, MyD88-dependent signals are responsible for early biofilm containment as typified by increased titers and infection dissemination in MyD88 KO animals." (PMID 22879997, 2012). "Once established infection proceeds similarly, although the MyD88−/− and TLR4−/− mice exhibit a delay in clearance relative to the TLR2−/− and C57BL6 mice (panels W6–10)." (PMID 22973560, 2012). "Both bioluminescence and CFUs were higher in the MyD88−/− mice, while p50−/− mice were found to be unable to clear C. rodentium, thus highlighting the significant functions of MyD88 and NF-κB in controlling the infection." (PMID 20955395, 2011). "We believe that an infection, probably viral, is the most likely explanation for the lesions observed in Myd88-IFNAR double-KO mice." (PMID 22216024, 2011). "It is possible that this MyD88-independent response resulted from heightened bacterial burdens observed in MyD88 KO animals at this interval post-infection." (PMID 21496301, 2011). "MyD88 KO mice were exquisitely sensitive to C. koseri and succumbed to infection within 24-36 h following bacterial exposure." (PMID 21496301, 2011). "Responses of cDCs to the bacterial RNA-containing extracts were fully abolished in MyD88-/- cells, which virtually mirrored the infection of cDCs with live S. pyogenes." (PMID 21625574, 2011). "Yet, even those neutrophils and macrophages that were recruited to the site of infection in MyD88 KO mice were less activated as revealed by reduced levels of cytokine/chemokine production." (PMID 21496301, 2011). "The role of TLR2/MyD88 in the differentiation of Lin− cells are in line with several previous reports showing that TLRs have a role in haematopoiesis during infection." (PMID 21935459, 2011). "The enhanced mortality rate of MyD88 KO mice was typified by significantly elevated bacterial burdens and attenuated cytokine/chemokine expression and immune cell influx early after infection (i.e. 12 h)." (PMID 21496301, 2011).
infection (continued). "Because S100B production mainly occurred in infection via the TLR2/MyD88 pathway, our findings indicate the existence of an autocrine/paracrine loop by which TLR2–induced S100B binds to extracellular RAGE to inhibit TLR2 upon physical association." (PMID 21423669, 2011). "Surprisingly, the levels of these same mediators were significantly increased in MyD88 KO animals at 24 h post-infection, suggesting a late induction of MyD88-independent signaling to elicit proinflammatory mediator release." (PMID 21496301, 2011). "The fact that TLR4 had little impact on the course of infection strongly suggests the involvement of alternative TLRs as well as the IL-1R and IL-18R, which also utilize MyD88 as an adaptor." (PMID 21496301, 2011). "Based on our previous report, C. pneumoniae-induced secretion of the cytokines TNF and IFNγ and the chemokines KC and MCP-1 depended on MyD88 three days post infection." (PMID 22096480, 2011). "Regional lymph nodes from MyD88−/− mice had similar cell numbers on day 10 of infection, with similar predominance of CD19+ B cells compared to control mice." (PMID 21637808, 2011). "In a similar infection model, MyD88 was recently found to be required for full blown immune response and survival." (PMID 21625574, 2011). "As IL-1β is produced in the cornea early after infection, it seems reasonable to assume that the MyD88 dependence is due to IL-1R1 signaling." (PMID 20617171, 2010). "Before infection with Mp or following mock infection, the majority of NFκB was distributed diffusely in the cytoplasm in both WT and MyD88−/− BMM." (PMID 21203444, 2010). "Despite the importance of TLR7/MyD88 signaling, MyD88-deficient mice can still produce type I IFN, control viral replication, and recover from the infection." (PMID 21108806, 2010). "The differences in virulence of the Δtssk-5 strain in wild-type and MyD88−/− infections suggest that T6SS-5 is required for effective defense of the bacterium against one or more innate immune responses of the host." (PMID 20865170, 2010). "The in vivo response to infection supports the conclusion that TcpC also suppresses Trif dependent effector functions, however, as Trif −/− mice have a functional Myd88 response, except for the cooperative TLR4 response to LPS." (PMID 20886104, 2010). "The same was true for Myd88−/− mice, in which the in vivo cytotoxicity assay was performed at an earlier post-infection time point (day 10 pi) due to their earlier mortality." (PMID 20442858, 2010). "Consistent with the proposed role of TcpC as a MYD88 inhibitor, in vitro infection with ΔTcpC upregulated MYD88 dependent transcripts involved in pathogen pattern recognition, compared to CFT073 infected cells (p>0.01)." (PMID 20886104, 2010). "MyD88 and IFN-γ signaling have been implicated in the generation of Tip-DCs in infection models including Leishmania, Brucella and Listeria." (PMID 20714353, 2010). "To address the role of TLRs and RLRs in stimulation of the IFN response during infection with C. pneumoniae, we infected wildtype (WT), myd88−/−trif−/− and mavs−/− MEFs with the bacteria and measured accumulation of ISG56 mRNA 18 h post infection." (PMID 20386592, 2010). "Tlr4−/− and Myd88−/− mice developed significant bacteriuria (≥105 CFU/ml of urine) six hours after infection with CFT073 or ΔTcpC and bacteria persisted in urine until the experimental end point." (PMID 20886104, 2010). "Respiratory syncytial virus (RSV) and SARS-CoV require MyD88 to produce an effective immune response to control severe infection in the lung." (PMID 20386712, 2010). "At day 5 post-infection, both MyD88−/− and TLR2−/− mice had reduced lung IL-6 concentrations when compared to WT mice." (PMID 21060793, 2010). "T. cruzi infection led to rapid increase in intracellular Ca2+ level in both wild-type and Myd88−/−Trif−/− Mφ, which returned to the basal level after 18 min of the infection." (PMID 19609356, 2009).
infection (continued). "TLR2−/− and MyD88−/− mice also showed increased bacterial burdens in lungs, liver, and spleen compared to controls following i.n. infection." (PMID 19936231, 2009). "Analysis of BAL fluid demonstrated a significant reduction in secretion of TNF in the lungs of TLR2−/− and MyD88−/− mice compared to control mice at 5 days post-infection." (PMID 19936231, 2009). "The type I IFN pathway has been suggested to mediate the most immediate TLR responses to infection, followed by MyD88 signaling inducing expression of pro-inflammatory cytokines like TNFα." (PMID 19656404, 2009). "To this effect, we observed that although MyD88 mice present with reduced immune cell activation following CB4 infection, they produce similar levels of TNF-α and CCL5 compared to WT mice." (PMID 19122812, 2009). "Following infection of MyD88KO mice, we observed reduced maturation of both macrophages and DCs compared to WT mice again suggesting a role for the MyD88 pathway in the maturation of APCs." (PMID 19122812, 2009). "The reduced survival time for the MyD88−/− mice also correlated with a greater increase in bacterial burden compared to TLR2−/− mice beginning on day 3 post-infection." (PMID 19936231, 2009). "The number of IFN-γ-producing CD4+ T cells was almost equally elevated in wild-type, Myd88−/− and Myd88−/−Trif−/− mice at 6 days as well as at 10 days after infection." (PMID 19609356, 2009). "In wild-type and Myd88−/−Trif−/− BMMφ, T. cruzi trypomastigotes infection induced nuclear translocation of NFATc1." (PMID 19609356, 2009). "In comparison, TNF-α−/−, MyD88−/−, IL-12−/− or IFN-γ−/− C57BL/6 mice, normally thought of as highly susceptible mice, display necrotic lesions only after 4 or 6 weeks of infection and mutilation is observed only after 8–10 weeks." (PMID 19557162, 2009). "Immune response-associated genes, with altered expression in virulent strain infection, were selected for further investigation: Tlr2, Tlr4, Tlr13, Myd88, Il1b, Il6, dectin-2 and Cxcl12." (PMID 19845042, 2009). "In the first 7 days after infection, viral levels were slightly higher in Myd88 null mice than in heterozygotes, but they reached a similar peak level at one week post-infection (wpi)." (PMID 19214214, 2009). "The increased hepatocellular injury in MyD88 KO mice after infection with B. pseudomallei was further underscored by clinical chemistry: MyD88 KO mice displayed strikingly higher plasma levels of ASAT and ALAT compared to WT mice." (PMID 18946505, 2008). "Relative to WT mice, MyD88 KO mice displayed strongly increased pulmonary and systemic bacterial loads at 24 and 72 hours after infection, as well as in their livers at 72 hours." (PMID 18946505, 2008). "Infection of WT, RAG-1−/−, or MyD88−/− mice resulted in weight loss beginning at day 2 post-infection." (PMID 19079579, 2008). "In line, local levels of the neutrophil attracting chemokines MIP-2 and KC tended to be lower or were significantly reduced in MyD88 KO mice at 24 hours after infection." (PMID 18946505, 2008). "In sum, these findings suggest that MyD88 is required for control of MA15 replication in pulmonary tissue at early times post-infection and that the inability to control or clear this early replication is associated with increased lethality." (PMID 19079579, 2008). "Here, we report that mice deficient in MyD88 (MyD88−/−), an adapter protein that mediates Toll-like receptor (TLR), IL-1R, and IL-18R signaling, are far more susceptible to rMA15 infection." (PMID 19079579, 2008). "While 100% of WT and 86% of RAG-1−/− mice survived the infection, >90% of MyD88−/− mice (n = 16) succumbed to infection by 6 dpi." (PMID 19079579, 2008). "To determine if the failure to recruit inflammatory monocytes/macrophages was sustained at later times post infection in MyD88−/− mice, we performed similar cell isolation experiments at 4 dpi." (PMID 19079579, 2008). "MyD88−/− mice had significantly higher viral loads in lung tissue throughout the course of infection." (PMID 19079579, 2008).
infection (continued). "The decreased bacterial clearance capacity of MyD88 KO mice was accompanied by a markedly reduced early pulmonary neutrophil recruitment and a diminished activation of neutrophils after infection with B. pseudomallei." (PMID 18946505, 2008). "The p38 MAPK inhibitor SB202190, the SAPK/JNK MAPK inhibitor JNK II, or both were added to Myd88−/− or WT macrophages at 120 minutes post-infection, the time of peak MyD88-independent, T4SS-dependent MAPK activation." (PMID 19043549, 2008). "At early times post rMA15 infection, the MyD88-dependent chemokine/cytokine response occurs with the recruitment of inflammatory monocytes/macrophages to the lung at 2 dpi and is coincident with the control of virus replication in WT animals." (PMID 19079579, 2008). "We cannot exclude that MyD88 dependent modulation of NADPH oxidase activity does play a role at later time point after cellular infection." (PMID 18946505, 2008). "At 72 h after infection TNFα levels remained lower in MyD88 KO mice, while MCP-1 and IL-6 levels tended to be higher in these animals." (PMID 18946505, 2008). "A total of 15 infected patients demonstrated significant upregulation of the innate immune pathway, including Toll-like receptor (TLR) signalling and the MyD88 cascade, suggesting an active immune response contributing to both infection control and bone resorption." (PMID 41937981, 2026). "Western blot results demonstrated that in IBV-infected CEK cells, baicalin significantly promoted the protein expression of IL-1β, IL-6, TNF-α, TLR7, and MyD88 at 24 h post-infection (hpi), whereas it markedly suppressed the expression of these factors at 48 hpi." (PMID 41375455, 2025). "As above, we found an increase in MyD88 protein levels after infection with wild-type virus." (PMID 40638072, 2025). "Notably, we found that at d15 post-infection, MyD88 levels were higher in the samples infected with the UL88-STOP virus than with WT TB40/E." (PMID 40638072, 2025). "Previous studies have highlighted the central role of TLRs in K. pneumoniae recognition with marked susceptibility to infection observed in the absence of TLR adaptors such as MyD88, TRIF, and TIRAP." (PMID 40248691, 2025). "To test this hypothesis, we treated TB40/E-mCh or UL88-STOP virus expressing an mCherry tag (UL88-STOP-mCh) with UV as above and examined both the spread of virus and levels of MyD88 at d12 post-infection compared to infection with each untreated virus." (PMID 40638072, 2025). "To confirm whether inhibition of HCMV spread by supernatant was mediated by a biologically active protein or lipid, we repeated the infection experiment in vector- and MyD88-transduced cells and collected supernatant at day 7 post-infection." (PMID 40638072, 2025). "Furthermore, FEBF effectively suppressed the PRV-induced upregulation of TLR4, MyD88, and NF-κB p65 proteins between 36 and 48 h post-infection." (PMID 40308697, 2025). "Since fewer MPO+, CD11b+, and MHC class II+ neutrophils were found in DKK1(PKO) and MyD88(PKO) infected mice, these data suggest that neutrophil persistent activation and migration to the infection site in BALB/c mice is promoted by DKK1 release via the MyD88 signaling pathway." (PMID 40502169, 2025). "Although we noted some interesting differences in the ability of S.Tm θ to infect MLNs and spleen in Myd88−/− and Ifngr1−/− mice, infection levels remained lower than wildtype S.Tm and further studies are needed to define the function of the spv operon at these distal sites of infection." (PMID 40462990, 2025). "In a mouse model of the Staphylococcus aureus (S. aureus) infection, the TLR2- and MyD88-deficient mice were highly susceptible, and the MyD88-deficient mice failed to recruit neutrophils to the infection site." (PMID 40006996, 2025).
infection (continued). "Indeed, the effects of UL88 were only apparent following a low MOI spread infection, likely because of the rapid and robust upregulation of MyD88 following exposure to a virus prep vs. the late expression kinetics of the tegument protein UL88." (PMID 40638072, 2025). "C. perfringens abundance was increased in NEC piglets and activation of TLR4 by Clostridia may occur in NEC as infection induced host immune responses involving TLR4/MyD88/NF-κB signaling pathways in piglets." (PMID 41283989, 2025). "Recent data from patients with inherited MyD88 and IRAK-4 deficiencies during the COVID-19 pandemic highlight their vulnerability to severe hypoxemic viral pneumonia and emphasize the need for aggressive supportive care and infection prophylaxis." (PMID 41369391, 2025). "Having examined the effects of MyD88, the target of UL88, upon the inflammatory response and the resulting inhibition of HCMV spread, we then moved to directly examine the effects of virus-encoded UL88 upon innate immune activation after infection." (PMID 40638072, 2025). "We wanted to investigate the expression of MyD88 upon MVA infection." (PMID 40981440, 2025). "We did find that induction of both IFN-β and IFNα2 transcripts was increased after infection with UL88-deficient HCMV, indicating that Type I IFNs could be the exogenous factor that slows HCMV spread in MyD88-transduced cultures." (PMID 40638072, 2025). "Notably, TLR signaling genes interferon regulatory factor 1 (IRF1) and MyD88 are significantly induced by MVA infection in DSK cells, probably to counterbalance the reduced IFN-I response of the cytosolic DNA-sensing cGAS/STING/IRF3 axis." (PMID 40981440, 2025). "However, the expression level of the MyD88 gene decreased in both groups (7.7-fold reduction during GI.1 (p = 0.02) and 2.7-fold reduction during GI.2 (p = 0.03) infection compared to the control)." (PMID 39273479, 2024). "Myd88-KO and Tlr7-KO mice also exhibited a strong increase in infection-induced death." (PMID 38777879, 2024). "Our previous work described MyD88-dependent production of IFNγ that was detected both at the site of infection and in the serum during the first few hours of N. caninum infection, but the cells producing IFNγ immediately after infection remained unknown." (PMID 39445806, 2024). "However, recent studies have highlighted that infection with viruses upregulates MyD88 expression and impairs the host antiviral response by negatively regulating type I IFN." (PMID 39125989, 2024). "The survival curves of the MyD88 mutant flies injected with T. marneffei displayed a clearcut phenotype, in which case nearly all of the flies finally succumbed to T. marneffei on the 14th day post infection (dpi)." (PMID 39239739, 2024). "Not only inhibition of this transcriptional plasticity through interference with RNA polymerase activity but also blockade of TLR4 sensing and its downstream signaling hubs, including NF-κB and MyD88, swiftly dampened infection-driven neutrophil shifts and subsequent phenotypic changes." (PMID 38517968, 2024). "Furthermore, TLR-4 at the cell membrane binds to its bacterial LPS ligand and recruits myeloid-differentiating factors, like MyD88, for an infection-induced inflammatory cascade." (PMID 39202716, 2024). "We have shown that exposure to natural infections promotes full-blown B-ALL in Pax5+/− mice and that the malignant transformation of preleukemic precursor B-cells is associated with reduced levels of Myd88 expression." (PMID 37620322, 2023). "Also, molecules such as TIMP-1, KC (CXCL1), and MIP-1 alpha (CCL3) showed inhibition upon E. japonica- infection in MyD88-independent manner." (PMID 38022511, 2023). "The infection phenotype of the MYD88−/− mice was distinct from both the WT and TLR2−/− mice." (PMID 37404047, 2023).